PARD3 (par-3 family cell polarity regulator)
Diseases named in the same sentence as PARD3 in open-access papers (continued):
Sharing a sentence is not in itself a finding about the gene and the disease.
hepatic diseases (1 paper, 2024). "As liver cancer is a long-term, progressively developing disease, we then examined whether PARD3 expression correlates with the progression of liver diseases towards liver cancer." (PMID 38317186, 2024). "In models of spontaneous liver cancer induced by choline-deficient, amino acid-defined (CDAA) and methionine-choline-deficient (MCD) diets, upregulation of PARD3 was induced specifically at the tumorigenesis stage rather than other early stages of liver disease progression." (PMID 38317186, 2024). "Interestingly, in the early stages of hepatic disease progression, there were no significant changes in the expression of PARD3, with PARD3 upregulation occurring only at the tumorigenesis stage." (PMID 38317186, 2024).
Hepatic fibrosis (1 paper, 2024). The presence of excessive fibrous connective tissue in the liver. "H&E staining revealed that liver inflammation was not affected by PARD3 knockout, and Masson trichrome (MT) staining showed no large difference in hepatic fibrosis between mice with PARD3 knockout and their wild-type littermates." (PMID 38317186, 2024).
keloid (1 paper, 2023). An irregularly shaped, elevated mark on the skin caused by deposits of excessive amounts of collagen during wound healing. "However, our results are innovative in revealing early wound healing-related genes (EPB41, TPM1, NF2, PARD3) in keloid patients from the perspective of alternative splicing regulated by RBP." (PMID 36777722, 2023). "We believe that the downregulation of PARD3 expression in KD42 may lead to a decrease in keratinocyte polarity, which in turn exacerbates the aggressiveness of the keloid." (PMID 36777722, 2023).
liver cancer (1 paper, 2024). An epithelial or non-epithelial malignant neoplasm that arises from the liver. "The CNAs characterized as “gains” or “amplification” result in an elevated number of copies of the PARD3 gene in the cancer cells’ genome, leading to higher levels of PARD3 mRNA and protein in liver cancer cells." (PMID 38317186, 2024). "High expression of PARD3 in tumour tissues was correlated with poor overall survival and recurrence-free survival in patients with liver cancer." (PMID 38317186, 2024). "To confirm the role of PARD3 in promoting the progression of established liver cancer, we established a stable clone of PARD3-overexpressing Hepa1-6 cells, a murine liver cancer cell line isolated from C57BL/J mice." (PMID 38317186, 2024). "In the case of PARD3, copy-number gains, which refer to an increased copy number of the genomic region encompassing the PARD3 gene compared to the normal state, were one of the most frequently observed CNAs in liver cancer." (PMID 38317186, 2024). "The natural compound berberine was selected as a potent suppressor of PARD3 expression and could be used as a preventive agent for liver cancer that completely blocks diet-induced hepatic tumorigenesis in a PARD3-dependent manner." (PMID 38317186, 2024). "Therefore, we speculate that CNAs likely play a role in the upregulation of PARD3 and may contribute to the neoplastic behaviour observed in liver cancer." (PMID 38317186, 2024). "By single-cell analysis, we showed that in an early established HCC tumour, PARD3 was enriched in cancer cells expressing CD133, the cell surface marker of liver cancer stem cells." (PMID 38317186, 2024). "To examine whether PARD3 expression is essential for metabolic stress-induced hepatic carcinogenesis, we used AAV-mediated gene transfer to conditionally knock out the hepatic expression of PARD3 in the murine models of CDAA diet-induced and MCD diet-induced liver cancer." (PMID 38317186, 2024).
liver cirrhosis (1 paper, 2024). "We extracted human data from GEO dataset GSE25097 and found that interestingly, PARD3 expression was not significantly induced at the stage of liver cirrhosis but was sharply induced at the stage of hepatic tumorigenesis." (PMID 38317186, 2024).
melanoma (1 paper, 2019). A malignant, usually aggressive tumor composed of atypical, neoplastic melanocytes. "The PARD3 mutated melanomas were also associated with a higher age at diagnosis, but this result was only marginally significant (χ2 = 4.00, p = 0.046)." (PMID 31745173, 2019).
metastatic tumors (1 paper, 2024). "In addition, the EMT regulatory factor snail is downregulated while the expression of E-cadherin is enhanced, highlighting the importance of PARD3 and snail-mediated EMT in metastatic tumors." (PMID 39063214, 2024).
pancreatitis (1 paper, 2020). Inflammation of the pancreas. "Certain genes, such as the myosin IXB (MYO9B) gene and its two close-connected adaptor genes, MAGI2 and PARD3, have been associated with pancreatitis as well as IBD." (PMID 32831829, 2020).
polycystic kidney (1 paper, 2013). "human PARD3/PARD6 knock-out in MDCK cell resulted in severe morphogenetic defect on three-dimensional culture condition, forming multiple lumen which is similar to polycystic kidney phenotype in human." (PMID 23349908, 2013).
Stroke (1 paper, 2022). Sudden impairment of blood flow to a part of the brain due to occlusion or rupture of an artery to the brain. "Furthermore, two signals (1q24 and 10p11) lie in genes reported to be associated with AD or stroke or have an important function in the brain (F5, and PARD3)." (PMID 35396452, 2022).
thyroid tumor (1 paper, 2019). A benign or malignant neoplasm affecting the thyroid gland. "When compared with adjacent non-tumor tissues, we found that miR-483 was upregulated and Pard3 was downregulated in 80 thyroid tumor samples." (PMID 30171257, 2019). "The increased cell migration and invasion may have resulted from the downregulation of Pard3 by miR-483 in thyroid tumor tissues following overexpression of miR-483." (PMID 30171257, 2019).
tumor (20 papers, 2009 to 2024). "Restoration of PARD3 expression significantly increased the risk of tumorigenesis in berberine-treated mice and increased the tumour multiplicity, tumour volume and serum AFP level." (PMID 38317186, 2024). "While the expansion of differentiated cancer cells upon PARD3 loss can lead to tumour enlargement, contradictory findings indicating that PARD3 overexpression promoted tumour progression in vivo have been obtained." (PMID 38317186, 2024). "The role of Pard3 is particularly important in the Par complex, and its abnormal expression will lead to loss of cell polarity and even tumor tumorigenesis." (PMID 36777722, 2023). "High PARD3 expression was associated with advanced T stage, pathologic stage, residual tumor, histologic grade, vascular invasion and higher alpha fetoprotein (AFP)." (PMID 34040099, 2021). "Several of the PTPRK substrates identified here have been linked to cancer, including PARD3 loss-of-function in invasion, and oncogenic and tumor suppressive roles for p120Cat." (PMID 30924770, 2019). "Besides, our tissue array multiplex IHC analysis showed that PARD3 was associated with cancer stemness and more aggressive tumor progression." (PMID 38317186, 2024). "Immune infiltration, which influences tumor purity, is one of the major risk factors in cancers, hence we quantified the enrichment scores (ECs) of 24 types of tumor-infiltrating immune cells (TIICs), in order to evaluate the association between PARD3 and immune infiltration levels in HCC." (PMID 34040099, 2021). "Since the restoration of PARD3 expression in LNCaP cells did not suppress tumor growth in subcutaneously injected nude mice (data not shown) we can suggest that mutational inactivation of the PARD3 gene could be a tumor-initiating event and occur at the level of the prostate stem cell." (PMID 19737411, 2009). "PARD3 inactivation-mediated loss of asymmetric cell division could lead to accumulation of stem or progenitor cells and to disruption of 3D tissue organization, resulting in the initiation of tumor formation." (PMID 19737411, 2009). "PARD3 knockout significantly reduced the expression of the tumour marker AFP in the liver, as well as the population of Ki67+ cells." (PMID 38317186, 2024). "The essential role of PARD3 in mediating hepatic tumorigenesis was assessed in diet-induced spontaneous liver tumour and syngeneic tumour models." (PMID 38317186, 2024). "Immunohistochemical analysis suggested that CD31 and Ki67 expression in PARD3-overexpressing Hepa1-6 tumours was higher than that in wild-type Hepa1-6 tumours." (PMID 38317186, 2024). "To evaluate the dynamic microenvironmental changes in early-stage tumours between the PARD3 wild-type and overexpressing groups, we analysed cell‒cell communication strength with CellChat." (PMID 38317186, 2024). "Compared to the individual drug, Erianin combined with 5-FU notably inhibited the expression of LKB1, SIK2, SIK3, and PARD3 in mouse tumor tissues." (PMID 39063214, 2024). "In contrast, cancer cell–cancer cell, cancer cell–fibroblast and cancer cell–myeloid cell communication was apparently upregulated in the PARD3 overexpressing early-stage tumour microenvironment." (PMID 38317186, 2024). "IHC and western blot analyses revealed that Erianin inhibited the expression of LKB1, SIK2, SIK3, and PARD3 in a dose-dependent manner in the mouse tumor tissues, and 5-FU also significantly reduced the levels of these proteins." (PMID 39063214, 2024). "The expression levels of DCAF1 and PARD3 in the tumor tissues of HCC patients (n = 20) were detected by IHC." (PMID 38711082, 2024). "In particular, single-cell sequencing analysis suggested that PARD3 was enriched in primitive tumour cells and its overexpression enhanced tumour-initiating cell (TICs)." (PMID 38317186, 2024). "H&E staining on the liver tumour sections revealed a more pronounced invasiveness at the tumour periphery in PARD3 overexpression orthotopic HCC mice." (PMID 38317186, 2024).
tumor (continued). "PARD3 expression was significantly upregulated in tumour tissues compared with adjacent normal tissues of patients with HCC." (PMID 38317186, 2024). "PARD3 overexpression significantly accelerated in vivo tumour growth in the liver and increased the incidence of lung metastasis of liver tumour cells." (PMID 38317186, 2024). "And a recent study has found that PARD3 drives tumorigenesis through activating Sonic Hedgehog signalling in tumour-initiating cells in liver cancer." (PMID 38711082, 2024). "Protein and gene expression analyses in patient samples revealed that SIK1, SIK2, SIK3, and PARD3 were all highly expressed in tumor tissues compared to adjacent normal tissues (p < 0.01)." (PMID 39063214, 2024). "PARD3 was overexpressed in tumour tissues and PARD3 overexpression was positively correlated with high tumour stage as well as the poor prognosis in patients." (PMID 38317186, 2024). "To confirm that the PARD3 overexpression-induced CD133+ cell population acquired tumour-initiating properties, we used an in vitro limiting dilution assay to measure the sphere-forming ability of PARD3-overexpressing CD133+ Hepa1-6 cells." (PMID 38317186, 2024). "The analysis of tumor tissue by immunohistochemistry showed a high expression of tight junction proteins PARD3, TJP2, and occludin (OCLN) in subcutaneous tumors formed by Nrp2−/− CRC organoids." (PMID 35158941, 2022). "This study showed that overexpression of miR-559 or PARD3 knockdown inhibited tumor angiogenesis by decreasing the expression of VEGF and Ang-2, two representative angiogenic factors." (PMID 36105681, 2022). "Potential covariates included adjacent hepatic tissue inflammation (39 points), T stage (75.5 points), age (67 points), tumor status (100 points) and PARD3 expression (90.25 points), and higher total points indicated worse prognosis." (PMID 34040099, 2021). "PARD3 is a gene involved in the regulation of cellular junction formation in ependymal cells, cilia, tumor suppression." (PMID 33935957, 2021). "We initially compared PARD3 expression between tumor and normal tissues in multiple cancer types using the UCSC Xena database." (PMID 34040099, 2021). "These include genes involved in hematological system development such as SETBP1 and NRP1 and putative tumor suppressor genes such as PARD3 and LRIG1." (PMID 28806978, 2017). "Contrary to our expectations, with regard to a possible tumor-suppressor role for the PARD3 gene, ectopic expression of the PARD3 gene in LNCaP cells resulted in a higher proliferation rate in tissue-culture." (PMID 19737411, 2009). "In addition, PARD3 overexpression potentially affected the ecosystem of early-stage tumours, as shown by the abundant fibroblast population and attenuated interactions with T cells." (PMID 38317186, 2024). "Lipid metabolism was activated in myeloid cells of PARD3 overexpressing tumours." (PMID 38317186, 2024). "Inhibition of SHH signaling may reduce the tumorigenicity of PARD3-overexpressing CD133+ tumor-initiating cells both in vivo and in vitro." (PMID 38730691, 2024). "However, as expected, PARD3 knockout significantly reduced the tumour burden in both CDAA diet-fed and MCD diet-fed mice." (PMID 38317186, 2024). "In PARD3-overexpressing CD133+ tumor-initiating cells, activation of SHH signaling was observed." (PMID 38730691, 2024). "Moreover, the crosstalk of cellular response of metal ion, metabolism and immune infiltration within tumor microenvironment may partly explain the function of PARD3 in HCC development." (PMID 34040099, 2021). "Alternatively, PARD3 inactivation could be a late event in the LNCaP tumor progression." (PMID 19737411, 2009). "PARD3 was enriched in HCC primitive tumour cells and its overexpression enhanced tumour-initiating cell (TICs)." (PMID 38711082, 2024).
tumor (continued). "As an essential component of the PAR complex that regulates the apical-basal polarity of epithelial cells, the role of PARD3 in EMT and tumor metastasis remains controversial, likely due to its context-dependent nature." (PMID 39063214, 2024). "To confirm the involvement of the PARD3-related pathway in hepatic carcinogenesis, we extracted total RNA from livers with or without surface tumours from C57BL/J mice after CDAA diet feeding for 54 weeks for transcriptomic analysis." (PMID 38317186, 2024). "Moreover, CD8+ T cell interacted with tumor cells and CAFs in the high HEC1 expression group by granzyme A (GZMA)—par‐3 family cell polarity regulator (PARD3)." (PMID 39021287, 2024). "Furthermore, overexpression of PARD3 enhanced tumorigenicity, tumor progression, and sustained the self-renewal ability of the CD133+ tumor-initiating cell population in HCC cells." (PMID 38730691, 2024). "Moreover, we performed functional enrichment and immune infiltration analysis to evaluate functional networks related to PARD3 in HCC and explore its role in tumor immunity." (PMID 34040099, 2021). "Moreover, we performed comparative transcriptome analysis, functional enrichment analysis and correlation analysis between PARD3 and immune cell infiltration to evaluate functional networks related to PARD3 in HCC and explore its role in tumor immunity." (PMID 34040099, 2021). "Non-tumor sections showed positive Pard3 staining, while tumor tissues showed a negative expression." (PMID 30171257, 2019). "Human PARD3 expression was detected in the plasma membrane of cells at the tumor core but not at the AOI." (PMID 25365423, 2014). "PARD3 wild-type and overexpressing cells were not distinguishable by the composition of major cell lineages except for fibroblasts, which were clearly more prevalent in the PARD3-overexpressing tumour microenvironment." (PMID 38317186, 2024).
cancer (11 papers, 2009 to 2025). A tumor composed of atypical neoplastic, often pleomorphic cells that invade other tissues. "Patients with higher level of PARD3 were associated an increased presence of CD133+ stem like cancer cell which was denoted as pink dots, further underlining the important role of PARD3 in TICs expansion." (PMID 38317186, 2024). "Loss of Pard3 has been shown to promote tumorigenesis in different human cancers via Tiam1/Rac1-dependent mechanisms." (PMID 30171257, 2019). "Deleterious mutations of PARD3 have been identified in several human diseases, including cancers." (PMID 38317186, 2024). "In differentiated epithelial-like cancer cells, loss of PARD3 has been extensively reported to regulate HIPPO signalling for the expansion of the cell population by directly interacting with and dephosphorylating YAP1 via its PDZ domain, which is essential for YAP1 activation." (PMID 38317186, 2024). "Correspondingly, we conducted GSEA on fibroblasts and myeloid cells to explore the potential functional changes induced by PARD3 overexpression in cancer cells." (PMID 38317186, 2024). "In agreement with this cancer-wide consensus, we report that low PARD3 mRNA levels among GBM patient samples in public databases, correlate with poor survival of the patients." (PMID 34642295, 2021). "The modulation of PARD3 in tumorigenesis and progression among different cancers seems to be controversial." (PMID 34040099, 2021). "PARD3 directly activates Rac1, promoting proliferation and motility of cancer cells, and leads to tumorigenesis, angiogenesis, invasion and metastasis." (PMID 34040099, 2021). "The preferential activation of SHH signalling by PARD3 in stem like cancer cells could contribute to the maintenance of their stem-like state, promoting self-renewal and inhibiting differentiation." (PMID 38317186, 2024). "Upregulation of PARD3 was observed specifically at the tumorigenesis stage in spontaneous liver tumour models, and knockdown of PARD3 inhibited hepatic tumorigenesis, while forced PARD3 expression accelerated cancer progression." (PMID 38317186, 2024). "Interestingly, our data and previous study suggested that PARD3 is differentially expressed in stem-like cancer cells and differentiated cancer cells." (PMID 38317186, 2024). "Communication between cancer cells and T cells was attenuated, suggesting that the increased stemness potential conferred by PARD3 overexpression may endow a higher potential for immune evasion." (PMID 38317186, 2024). "Based on TCGA database, PARD3 expressed differentially in 24 types of cancers." (PMID 34040099, 2021). "Subsequent pseudotime analysis of the cancer cell population showed that PARD3 was preferentially enriched in cancer cells at early developmental stages but not in those at differentiated stages, further indicating the essential role of PARD3 as a driver of self-renewal maintenance in TICs." (PMID 38317186, 2024). "Contradictorily PARD3 could either promote or suppress EMT in different types of human cancers." (PMID 38317186, 2024). "Our scRNA sequencing analysis demonstrated a positive correlation between the expression of PARD3 and CD133 in the cancer stem cell lineage with highly activated SHH signalling." (PMID 38317186, 2024). "In addition, the phosphorylation of aPKC was significantly correlated with the expression of Gli1, PARD3 and Sox2 (R > 0.4), emphasizing the important role of aPKC in mediating PARD3, SHH signalling and cancer stemness." (PMID 38317186, 2024). "Pathways derived from NOTCH3, PARD3, CACNA1A, MAX, RAD50, FUS and LMO2 were cancer-related." (PMID 34540367, 2021). "Inhibiting PARD3 activity could potentially impede the transformation of normal liver cells into cancer cells, thereby preventing tumorigenesis." (PMID 38317186, 2024).
liver (2 papers, 2009 to 2024). "We therefore examined the expression of PARD3 in the liver during metabolic dysfunction-associated liver carcinogenesis." (PMID 38317186, 2024).
gastrointestinal disorders (1 paper, 2019). "Polymorphisms in TJ-related genes MAGI2, PARD3, and MYO9B that potentially influence the homeostasis of the intestinal barrier have been associated with risk of gastrointestinal disorders like CD and IBD." (PMID 31921880, 2019).